MMP2 (matrix metallopeptidase 2)
Diseases named in the same sentence as MMP2 in open-access papers (continued):
Sharing a sentence is not in itself a finding about the gene and the disease.
tumor (continued). "Existing literature shows MMP2 not only degrades the basement membrane and matrix to break through the matrix barrier, thus promoting tumor invasion and metastasis, but also accelerates tumor growth and proliferation through neovascularization." (PMID 33115469, 2020). "MMP‐2, expressed in our primary cells, may be related to the invasion of tumor cells and the development of the tumor vascular supply by allowing entry of endothelial cells during angiogenesis." (PMID 32652895, 2020). "It has been shown that MMP-2 may affect tumor viability and invasiveness also by regulating lymphangiogenesis." (PMID 33198257, 2020). "Our in vivo tumorigenicity model also showed the effects of JAM-B on promoting tumor incidence, the time to tumor appearance, tumor size, tumor weight, and the expression of related factors such as c-Src, E-Cadherin, MMP-2 and MMP-9, which provided necessary support for future mechanistic studies." (PMID 32231730, 2020). "Additionally, IL32 expression did not correlate with genes associated with disease progression, tumor cell invasion, and migration, such as CD155/PRV and MMP2." (PMID 30953519, 2019). "The florescence assays revealed that it could enter into tumor cells by the enzyme digestion of MMP-2/9." (PMID 31346326, 2019). "In the EMT process of tumor cells, expression of proteins promoting cell-cell contact such as E-cadherin is decreased, while expression of mesenchymal markers such as vimentin, MMP-2 and -9 is increased, resulting in cell migration and invasion ability is enhanced." (PMID 30862004, 2019). "It was determined that MTA2 is an oncogene and a poor prognostic factor for the OS of HCC patients and that changes in p38MAPK-mediated MMP2 expression may contribute to tumor metastasis." (PMID 31777601, 2019). "Thus, trans-manner complex formation between CD73 on fibroblasts and emmprin on tumor cells possibly regulates MMP-2 production from fibroblasts." (PMID 31510956, 2019). "Additionally, it has been observed that MMP-2-positive tumor cells in patients are correlated with low mean survival." (PMID 31921634, 2019). "Interestingly, we found a nearly 50% reduction in MMP-2 expression in TNBC tumor sections after electroacupuncture treatment compared to the sham EA group (**P < 0.01)." (PMID 31839752, 2019). "Meanwhile, BA treatment also decreased the expression level of Ki‐67 and MMP‐2 in tumour cells." (PMID 30417527, 2019). "Therefore, we proposed that the knockdown of MTA2 downregulates the expression of MMP2, inhibiting tumor metastasis in HCC." (PMID 31777601, 2019). "The MMP-2 in the stroma decreased with increasing node size; however, this correlation was not statistically significant, and the expression was significantly higher than in tumor." (PMID 31223594, 2019). "In summary, MMP2 is a key molecule in all aspects of tumor growth and metastasis." (PMID 31709184, 2019). "The suppressive effect of CA on MMP-2 and MMP-9 is associated with blockade of the activation of NFkB, as reported in liver cancer cells stimulated by PMA (activating protein 1), leading to a decrease in tumor growth and invasiveness." (PMID 31293975, 2019). "Moreover, in the differentiation between PC and CP patients, the AUC for TIMP-2 (0.6532, p = 0.004) was higher than for MMP-2 (0.5378, p = 0.47), but lower than AUC for classical tumor marker (CA 19-9 – 0.7765, p < 0.001; CEA – 0.7193, p < 0.001)." (PMID 30719232, 2019). "As a member of MMPs, MMP2 is widely regarded as a marker of tumor invasion and metastasis." (PMID 31598171, 2019). "A significant increase in the odds ratio for survival occurred in the case of increased expression of MMP-9 investigated in the tumor and MMP-2 and TIMP-1 in the stroma; however, the chance of the patient’s survival increased most clearly in relation to TIMP-1P [OR=1.724]." (PMID 31223594, 2019). "The MMP-2 protein contents of the transplanted tumor varied among groups in a similar fashion." (PMID 30789971, 2019).
tumor (continued). "Lactate shuttle between CAFs (released by MCT4) and tumor cells (absorbed via MCT1) may accelerate tumor cell invasion by activation of TGF-β1/p38 MAPK/MMP2/9 signaling." (PMID 31737570, 2019). "This upregulation in MMP expression might have enhanced the motility of these cells because the invasion of tumor cells is mainly dependent on the degradation of extracellular matrix by MMP-2 and MMP-9." (PMID 31572058, 2019). "Similarly, the indicators for tumor development and progression, MMP-2 and MMP-9 were also inhibited by KLF8 silencing, which just proved the alterations of tumor malignancies at molecular level." (PMID 31827393, 2019). "MMP-2 is a collagenase that represents the main proteolytic enzyme among MMPs and is a major promoter of tumor cell invasion and metastasis through breaking down of the basement membrane and favoring the local and distant infiltration of tumor cells." (PMID 31886121, 2019). "To further investigate whether DDX17 affected the expression of Klf4 target genes responsible for tumor metastasis, we checked the expression of E-cadherin and MMP2, whose promoter or enhancer element is regulated by Klf417,20." (PMID 31653828, 2019). "In addition, we also detected the expressions of E-cadherin, N-cadherin, Matrix metalloproteinase (MMP)-2 along with MMP-9, which are closely associated with tumor metastasis capacity by western-blot." (PMID 31164797, 2019). "Moreover, sICAM-1 exposure also promoted tumor secretion of matrix remodeling factors uPA, MMP-2, and MMP-9." (PMID 31511625, 2019). "In this study, we identified new molecules which formed a complex with emmprin in co-cultures of tumor cells and fibroblasts and analyzed whether these molecules were involved in the regulation of MMP-2 production." (PMID 31510956, 2019). "Once activated, tumor associated myeloid cells contribute to tumor proliferation by secreting oncogenic factors such as EGFR, extracellular matrix (ECM) remodeling by releasing proteases such as MMP2 and MMP14 and induction of angiogenesis by secretion of proangiogenic factors." (PMID 32038644, 2019). "When the LOX inhibition group was compared with the control group, the enzyme activity of the active form of MMP-2 (62 kDa) in mouse tumor tissues was significantly decreased (P < 0.05) and the enzyme activity of the active form of MMP-9 (92 kDa) was significantly decreased (P < 0.05)." (PMID 31777578, 2019). "In conclusion, the enhanced metastasis and invasiveness of LPL-expressing tumor cells may be synergistically mediated by regulation of peripheral actin elasticity and MMP2 transport to invasive sites." (PMID 31501427, 2019). "However, TAMs were also found to directly contribute to tumor niche formation and tumor ECM shaping by producing proteolytic enzymes (MMP-2 and MMP-9) and matrix-associated proteins." (PMID 31591367, 2019). "We also found the tumor microenvironment, in terms of the number of tumor-associated macrophages, microvascular density, and expression of matrix metalloproteinase-2 (MMP-2), in the recurrent tumor after radiotherapy is different between primary tumor core and tumor edge." (PMID 31106146, 2019). "Additionally, T3 inhibits cell invasion and metastatic potential via inducing DKK4 expression by reduction of matrix MMP2 and downregulation of the transcription factor ELF2 associated with tumor growth and cell proliferation." (PMID 31600974, 2019). "So the 18F-NOTA-iCREKA could keep stable before it reached the tumor and then took effect after digestion by MMP-2/9 in the tumor stroma." (PMID 31346326, 2019). "Interestingly, nano preparations accumulated in tumour sites and cleavable MMP2 peptide was broken, which allowed the exposure of TAT promoting cell internalization and drug release." (PMID 30634689, 2019).
tumor (continued). "Lysophospholipids and adrenomedullin stimulate insertion of the channel into the plasma membrane, and the subsequent TRPV2-mediated Ca2+ influx increases invasiveness of tumor cells via the direct regulation of key proteases such as MMP2, MMP9, and cathepsin B." (PMID 31288452, 2019). "GLUT1 expression is significantly correlated with MMP2 expression in tumor cells." (PMID 31598171, 2019). "18F-NOTA-iCREKA was stable in vitro and could get high uptake in MMP-2/9 highly expressed U87MG tumor cells while the uptake in MMP-2/9 lowly expressed Caov3 cells was extremely low." (PMID 31346326, 2019). "Also, MMP-9 and MMP-2 played an important role in the prediction of tumor recurrence and survival in HCC patients after surgical resection." (PMID 31831037, 2019). "MMPs are a family of zinc-dependent matrix-degrading proteases that have a crucial role in tumor metastasis, in which MMP2, MMP9, and MMP14 are the three major proteinases among MMP subfamily members involved in pericellular proteolysis associated with cell migration." (PMID 31093311, 2019). "It has been confirmed in mouse implanted with human HCC that inhibition of STAT3 activation by antisense oligonucleic acid not only reduces the expression of VEGF and MMP-2 but also reduces the microvascular density (MVD) of CD34 positive in tumor tissues, inhibiting tumor metastasis to the liver." (PMID 31885639, 2019). "Additionally, a correlation study revealed a strong positive correlation between tumour angiogenesis (as demonstrated by VEGF levels) and tumour cell metastasis tendency (as demonstrated by the MMP-2:TIMP-1 ratio) (P < 0.001)." (PMID 31836811, 2019). "In CCL9-expressing CMT93 colon carcinoma, CCR1+ neutrophils secrete MMP9 to foster cancer foci, and in late phases of tumor the neutrophils recruit fibrocytes or induce differentiation from monocytes to fibrocytes which secrete MMP2, accommodating tumor cell colonization." (PMID 31474975, 2019). "Literature has already hypothesized the interaction of CTX and MMP-2, a protein highly upregulated during tumor production." (PMID 31857956, 2019). "Moreover, MT1-MMP, as one of the raft-affiliated matrix metalloproteinases (MMPs), has been shown to contribute to the invasive abilities of tumor cells by activating pro-MMP-2." (PMID 31101050, 2019). "This fibrin-binding iCREKA could be a potential probe and carrier of therapeutic drugs for the MMP-2/9 highly expressed tumor." (PMID 31346326, 2019). "Moreover, the downregulation of LRG-1 also reduced the expression of critical factors participating in tumor metastasis, including MMP-2 and MMP-9." (PMID 30760292, 2019). "More than the degradation of extracellular proteins, some MMPs regulate tumor invasion through other mechanisms, for example, MMP-2 as well as MMP-9 could activate TGF-β to promote tumor invasion." (PMID 31406154, 2019). "It is well known that MMP2 is a marker of tumor invasion and metastasis." (PMID 31598171, 2019). "These NPs could be reduced in the tumour by enzymes (matrix metallopeptidase, MMP-2) and thus highly release in the tumour site Ato and ICG-BSA after only 2 h." (PMID 31671658, 2019). "To test the hypothesis that DKK1 promotes tumor invasion, we performed gelatin zymography, western blot and qPCR to assess the expression pattern of gelatinases (MMP-2, MMP-9)." (PMID 31568519, 2019). "The functional blocking of PTTG1 may induce suppression of tumor growth and metastasis development, by the down-regulation of MMP-2 expression." (PMID 31572301, 2019). "Thus, we further investigated the ability of circPUM1, in the form of exosomes, to regulate the peritoneal expression of MMP2 and promote the dissemination of tumor foci and cancer progression." (PMID 31751911, 2019). "MMP-2 is a key promotor in the migration and invasion of tumor cells by degradating ECM." (PMID 29684087, 2018).
tumor (continued). "However, a higher increase in MMP-2 expression levels was found in total tumor cells (% of increase, stressed vs control: 169) respect to immune cell-depleted suspensions (72%)." (PMID 29971064, 2018). "Interestingly, MMP2 is delivered by tumour‐infiltrating immune cell 38, which are considered markers of higher endothelial permeability." (PMID 29044946, 2018). "Importantly, TIPE1 dramatically restrained the expression and activities of MMP2 and MMP9 which are demonstrated to promote tumour progression and are implicated in EMT." (PMID 28994231, 2018). "Based on our data, however, AQP1‐dependent reduced angiogenesis could also be due to the reduced amount of MMP2 found in AQP1 siRNA‐treated tumours." (PMID 29044946, 2018). "In particular, MMP-2 plays a critical role in tumor cell invasion and metastasis." (PMID 30225259, 2018). "Consequently, specific penetration of iCREKA into tumor cells can be achieved only after iCREKA is cleaved by MMP-2/9." (PMID 29686590, 2018). "Increased expression of MMP2 has been shown to promote the invasion and metastasis of tumour cells." (PMID 29330507, 2018). "The increased availability of Mmp2 and Mmp12 as well as their substrates Col1a1, Col4a1, Col6a1 and LamC2 could indicate that the tumour cells generated foremost collagens, which can be cleaved by these Mmps." (PMID 30603057, 2018). "Matrix metalloproteinases (MMPs) play a central role in the invasion process by degrading many elements of the extracellular matrix (ECM), including collagens, fibronectin and laminins, and suppression of MMP-2/-9 expression represents a potential strategy for preventing tumor cell invasion." (PMID 29538296, 2018). "Many tumours have shown to overexpress MMP-2, the advantage of which could be explored to target drugs to tumour sites." (PMID 30082647, 2018). "In addition, MMP-2, known as another gelatinase of MMP family except for MMP-9, is also associated with tumor invasion in PAs." (PMID 32922863, 2018). "Its members MMP-9 and MMP-2 are closely related to tumor metastasis." (PMID 30580327, 2018). "Two MMPs were identified based on their respective molecular weight corresponding to MMP9 (92 kDa) and MMP2 (72 kDa) Analysis of the relative amount of enzyme in the tumour cell conditioned medium showed a dose-dependent expression of MMPs activities with a predominant activity for MMP2." (PMID 29563634, 2018). "The pulmonary tumour nodules were then evaluated for the expression of MMP2." (PMID 29148232, 2018). "In lung tissues, treatments with antrodan only (20 mg/kg and 40 mg/kg), and cisplatin only (1 mg/kg) significantly reduced protein expression of MMP-2, with reductions of 38.3% (p < 0.05), 49.9% (p < 0.05), and 48.1% (p < 0.05), respectively, when compared with the tumor control group." (PMID 29794990, 2018). "MMPs, and in particular MMP-2, may also support tumor dormancy, releasing bioactive fragments of ECM that can inhibit angiogenesis, such as endostatin, restin, arrestin, and all three chains of type IV collagen." (PMID 29874869, 2018). "DEHP and MEHP can also promote tumor cell migration and invasion by activating MMP2." (PMID 29568348, 2018). "Importantly, HGF-induced tumor cell motility and invasion are accompanied by an increase in cell dissociation and protease production [e.g., MMP-2 and urokinase-type plasminogen activator (uPA)]." (PMID 30352967, 2018). "The mechanism for MAHNP-DOX accumulation in cells and nuclei should be similar to the mechanism for free DOX because this peptide-conjugated DOX can be cleaved into free DOX by MMP-2 that is mainly secreted by stromal cells and distributed abundantly around tumor cells in the extracellular matrix." (PMID 29405790, 2018). "MMP-2 has been reported to be related to tumorigenesis, tumor invasiveness, and metastasis." (PMID 29949618, 2018).
tumor (continued). "Data from immunofluorescence studies showed that dihomo-γ-linolenic acid supplementation increased the expression of MMP-2 (a marker for tumor metastasis) in delta-5-desaturase-WT tumors, while significantly decreasing MMP-2 expression in delta-5-desaturase-KD tumors." (PMID 30567534, 2018). "Tumor tissues also overexpress MMP-2/9 and hydrolytic enzymes." (PMID 29686590, 2018). "In addition, studies have reported that cyclin D1, cyclin E, MMP-2 and MMP-9 are associated with tumor growth and metastasis inhibition in an A549 cell and its xenograft mouse tumor model." (PMID 29522490, 2018). "They suggested that MMP-2 could be a marker of tumour aggressiveness, and MMP-2 inhibitors could be used in therapy." (PMID 30539028, 2018). "Down regulation of MMP-2 in the primary tumor revealed unfavourable outcome of the disease." (PMID 29316907, 2018). "Upon binding of the peptide conjugates to αvβ3 integrins, significant expression of MMP-2/9 in tumor vasculature was hypothesized to ensure drug release at the target site." (PMID 30241287, 2018). "Notably, several studies showed that SFN down-regulated MMP-2 expression in different tumor cell lines, modulating cellular survival pathways, such as ERK1/2." (PMID 30441761, 2018). "Based on our findings, PHLPP2 may function as a tumor suppressor by activating p62 transcription and expression, which further induces autophagy and promotes MMP2 degradation." (PMID 29930380, 2018). "Targeting MMP-2/9 in tumor tissues has been attempted in targeted cancer therapies." (PMID 29686590, 2018). "In addition, these molecular probes were able to achieve a tumor cell-penetrating effect after cleavage by MMP-2." (PMID 29686590, 2018). "MSC-derived exosomes can modulate the function of tumor cells through induction of MMP-2 and ecto-5′-nucleotidase activity, thus enhancing the heterogeneity within the tumor microenvironment, while they also enclose tumor supportive micro RNAs, which enhance tumor growth." (PMID 30526687, 2018). "Strikingly, NF-κB is reported to play a key role in tumor migration and has a synergistic expression pattern with MMP2, which suggests that MMP2/NF-κB could be involved in phycocyanin-induced migration inhibition regulation in NSCLC cells." (PMID 29882874, 2018). "Interestingly, genotype tumor cells was more important than the host stromal component in promoting MMP-2/-9 activity in the tumors in this model system." (PMID 30400822, 2018). "However, high expression of MMP2 and MMP9, alone and in combination has been associated with tumour progression in HCC." (PMID 29346427, 2018). "Both MMP-2 and MMP-9 are markers associated with the tumor invasion and metastasis." (PMID 30960968, 2018). "Then we analyzed the protein levels of those tumor-related genes, and found that both β3GnT8 and β3GnT2 could markedly elevate MMP2 and MMP14 expression." (PMID 29875690, 2018). "As the invasive ability of tumor cells is often correlated with the production of secretory proteases, the effect of HDGF knockdown on the expression of tumor invasion-associated secretory proteases MMPs including MMP2 and MMP9 were determined." (PMID 29300772, 2018). "Moreover, NF-κB signal pathway seemed to be able to suppress tumor cell migration by blocking MMP-2 and MMP-9 expression." (PMID 30519264, 2018). "Testing whether TGF-β and pro-inflammatory TNF/IL-1β cytokines cooperate in the regulation of MMP9, we found that MMP9 expression was induced only in tumor cells, while fibroblasts expressed high levels of MMP2." (PMID 28423685, 2017). "Using these cell models, we unveiled two distinct roles of PDE5 in attenuating GBM aggressiveness: 1) decreased tumor cell invasion and migration via stabilization of acto-myosin interactions and decreased MMP-2 secretion; 2) enhanced radio-sensitivity by inhibiting DNA repair." (PMID 28099939, 2017).